CHLSN (cholesin)
Description:
Hormone secreted from the intestine in response to cholesterol, where it acts to inhibit cholesterol synthesis in the liver and VLDL secretion,leading to a reduction in circulating cholesterol levels. Acts through binding to its receptor, GPR146.
Synonyms: C7orf50; MGC11257; YCR016W
Tractability: Antibody: UniProt places it where antibodies can reach, with high confidence; its Gene Ontology location is reachable by antibodies, with medium confidence.
Gene: Protein-coding gene on chromosome 7 (996,973 to 1,138,313, reverse strand). Ensembl gene ENSG00000146540.
Subcellular location: Secreted
Subcellular location (Human Protein Atlas): Nucleoli; Nucleoplasm
Gene Ontology:
Molecular function: hormone activity; protein binding; RNA binding
Biological process: negative regulation of cholesterol biosynthetic process; signal transduction
Cellular component: extracellular region
Genetic constraint (gnomAD): Loss-of-function variants: 14 observed, 16.54 expected, observed/expected ratio (o/e) 0.85, 90% interval 0.56 to 1.32. The upper end of that interval is the gene's LOEUF score, 1.32, which puts it in group 5 of 6, group 1 being the genes least tolerant of losing a copy. Missense variants: 281 observed, 238.91 expected, observed/expected ratio (o/e) 1.18, 90% interval 1.07 to 1.3. Synonymous variants: 136 observed, 109.08 expected, observed/expected ratio (o/e) 1.25, 90% interval 1.08 to 1.44.
Homologues: Orthologues: chimpanzee CHLSN (82% identical), guinea pig CHLSN (64% identical), mouse Chlsn (61% identical), pig CHLSN (56% identical), rat C12h7orf50 (53% identical), zebrafish zmp:0000000624 (42% identical).
Diseases named in the same sentence as CHLSN in open-access papers:
CHLSN is named in the same sentence as 9 diseases in open-access papers, as found by Europe PMC text mining. Sharing a sentence is not in itself a finding about the gene and the disease. The quoted sentences say what the papers report.
colorectal carcinoma (1 paper, 2024). A malignant epithelial neoplasm that arises from the colon or rectum and invades through the muscularis mucosa into the submucosa. "Using human colorectal carcinoma cells that stably expressed cholesin, the group also observed that cholesin was secreted to the medium proportional to varying doses of administered cholesterol, and this process was impaired with NPC1L1 knockdown, the intestinal cholesterol transporter." (PMID 39872505, 2024).
Obesity (1 paper, 2025). Accumulation of substantial excess body fat. "The cholesin gene c7orf50 was robustly expressed throughout the intestinal tracts of both individuals with type 2 diabetes and healthy controls, as well as in the livers of men with and without obesity." (PMID 40004948, 2025).
type 1 diabetes (1 paper, 2025). "Although the robust expressions of c7orf50 and GPR146 in the adipose tissue of individuals with type 1 diabetes suggest a potential role of the cholesin system in adipose tissue, these findings must be interpreted with caution without data from an appropriate control group." (PMID 40004948, 2025).
CHLSN also shares sentences with these, for which no sentence is quoted: cancer (2 papers); breast carcinoma (1); pancreatic cancer (1); pituitary tumor (1); schizophrenia (1); type 2 diabetes (1).